BCR (BCR activator of RhoGEF and GTPase)
Diseases named in the same sentence as BCR in open-access papers (continued):
Sharing a sentence is not in itself a finding about the gene and the disease.
myelofibrosis (11 papers, 2019 to 2025). A partial or complete replacement of the bone marrow stroma by fibrous tissue. "On top of this, quantitation of mutant burden in the patients can provide important clinical information such as transformation to myelofibrosis and drug responses in the patients with BCR::ABL1-negative MPNs." (PMID 37629188, 2023). "In rare cases, patients with primary myelofibrosis may undergo leukemic transformation involving the emergence of a BCR::ABL1-positive clone." (PMID 40734882, 2025). "In adults PMF and post-ET/PV myelofibrosis (post-ET/PV MF) are BCR::ABL1-neg MPNs with the worst survival rates, but allo-HCT can cure a substantial number of patients, especially those younger than 70 years and with a median survival expectation of less than 5 years." (PMID 38627449, 2024). "The subtle morphologic diagnosis and differentiation between coexisting JAK2 V617Fpos MPN and BCR::ABL1pos CML is complicated by the fact that left-shifted leukocytosis, thrombocytosis, BM hypercellularity and myelofibrosis can variably occur in both entities." (PMID 40681596, 2025). "The patient was diagnosed with CML blast crisis of the acute megakaryoblastic leukemia subtype (M7), presenting with BCR/ABL1 fusion gene positivity, complex karyotypic abnormalities, and secondary myelofibrosis." (PMID 41341402, 2025). "Among MPN patients, 36% (4/11) had BCR-ABL fusions, and 27% (3/11) had myelofibrosis." (PMID 40335619, 2025). "In children and adolescents myelofibrosis (MF) is the rarest type of BCR::ABL1-neg MPNs, and so far there was no study analysing the outcomes of allo-HCT in a larger group of paediatric patients with MF, and therefore the data on allo-HCT outcomes in them remain casuistic and scant." (PMID 38627449, 2024).
Thrombocytosis (11 papers, 2011 to 2025). Increased numbers of platelets in the peripheral blood. "In the present study, we report a case of CML (41 years, female) with extreme thrombocytosis at onset, with the variant Ph chromosome and rare e14a3 (b3a3) BCR::ABL1 transcript." (PMID 36354705, 2022). "As previously published, testing for BCR::ABL1 fusion in patients with known BCR::ABL1-negative MPN was prompted by new-onset leukocytosis, whereas testing for driver mutations in patients with known CML was prompted by new-onset thrombocytosis." (PMID 40906032, 2025). "Moreover, patients with isolated thrombocytosis should be routinely examined for BCR/ABL fusion gene, in order to effectively avoid the misdiagnosis of this specific CML population." (PMID 34477162, 2021). "Therefore, in case of persistent thrombocytosis without leukocytosis and negative driver mutations, BCR::ABL1 will be researched to avoid missing atypical presentation of CML." (PMID 36980287, 2023). "In addition, BCR/ABL fusion gene examination in patients with thrombocytosis might represent an effective strategy to avoid the misdiagnosis of this specific CML population." (PMID 34477162, 2021). "Since cases with thrombocytosis were assessed only in terms of the frequency of JAK-2 mutation in that study and the frequencies were found to be different from those in other studies that assessed the frequency of JAK-2 mutation in cases with BCR‐ABL‐negative CMDs." (PMID 29732039, 2018). "In CML patients, the persistence or occurrence of thrombocytosis, despite WBC decrease and good molecular BCR::ABL1 response under TKI, should alert clinicians to perform molecular screening for Ph-negative MPN, including JAK2, MPL, and CALR mutations." (PMID 38596359, 2024). "The research of BCR::ABL1 is an important step for differential diagnosis in the case of persistent leukocytosis and/or thrombocytosis (after eliminating reactional events), notably, if there are few myeloid precursors." (PMID 36980287, 2023). "On the basis of the high frequency of megakaryocyte involvement in CML patients and the concurrent thrombocytosis in our patient, we assumed that platelet dysfunction was a manifestation of CML and that the megakaryocytes also carried the BCR-ABL fusion gene." (PMID 21624109, 2011).
lung carcinoma (10 papers, 2012 to 2023). "High-throughput sequencing has also indicated the causality between mutations or fusions of some kinases with cancers, the most famous examples of which are L858R and T790M EGFR mutations in lung cancer and BCR-ABL fusion genes in chronic myeloid leukemia." (PMID 32944406, 2020). "These associations include APC/CDC20 for EML4-ALK fusions in lung cancers, SPOP for NUP98-NSD1 and BCR-ABL fusions in LAML, and FBW7 (or FBXW7, F-box and WD repeat domain containing 7) for CCDC6-RET fusions in thyroid carcinomas (THCAs)." (PMID 34795215, 2021). "These approaches are important milestones but however fail to account for patients who receive targeted therapy as standard of care such as EGFR inhibitors in lung cancer or BCR/ABL inhibitors in CML." (PMID 30551737, 2018). "There are already several examples of such personalized treatments including the drug Gleevec that targets the BCR-ABL fusion gene in chronic myelogenous leukemia (CML) and Iressa that targets the EGFR gene in lung cancer." (PMID 23300412, 2012). "Well-characterized examples include the BCR-ABL translocation in Philadelphia chromosome-positive leukemias, which confers sensitivity to the ABL tyrosine kinase inhibitor imatinib, as well as epidermal growth factor receptor (EGFR)-mutant lung cancers, which are sensitive to EGFR inhibition." (PMID 27855189, 2016).
myelodysplastic syndrome (10 papers, 2014 to 2023). A clonal hematopoietic disorder characterized by dysplasia and ineffective hematopoiesis in one or more of the hematopoietic cell lines. "Initially, both the myelogram and the BCR mutation genetic test allowed us to reject suspicions of a myeloproliferative process and myelodysplastic syndrome (MDS)." (PMID 27363711, 2017). "However, tyrosine kinase inhibitors have cytotoxic effects in only a few hematologic malignancies with BCR-ABL fusion genes including CML, myelodysplastic syndrome, and BCR-ABL-positive MM." (PMID 35342415, 2022). "Given that the duration of CML-CP development by BCR–ABL retrovirus is about 3–4 weeks, and Evi1 alone could induce myelodysplastic syndrome/AML in mice after 6 months or more, these results indicate that Evi1 can have a causative role in blastic transformation of CML." (PMID 24747972, 2014).
leukocytosis (9 papers, 2018 to 2026). "All 8 patients with JAK2 fusion genes (PCM1, n = 7; BCR, n = 1; male 7/8; median age 69 years, range 29–73) presented with leukocytosis (median 25.9 × 109/l, range 10.5–55.0)." (PMID 37454239, 2023). "Our patient’s marked leukocytosis warranted further evaluation with peripheral blood flow cytometry, and subsequent FISH analysis to confirm BCR-ABL fusion." (PMID 35573502, 2022).
B-cell Acute Lymphocytic Leukemia (8 papers, 2018 to 2025). "The IKZF1 gene, which encodes the Ikaros transcription factor, is frequently deleted or mutated in patients with B-cell precursor acute lymphoblastic leukemias that express oncogenes, like BCR-ABL, which activate the JAK-STAT5 pathway." (PMID 33180866, 2020). "Extended co-culturing of DNA barcoded mouse BCR/ABLp185+ B-cell acute lymphoblastic leukaemia (B-ALL) cells with NK cells allowed for a quantitative measure of NK cell–mediated immunoediting." (PMID 39642167, 2025). "The Philadelphia chromosome (Ph), which leads to the creation and expression of the fusion gene product BCR-ABL, underlines the pathogenesis of chronic myelogenous leukemia (CML) and a fraction of adult and pediatric acute B-lymphoblastic leukemia (B-ALL)." (PMID 32552902, 2020). "B-cell acute lymphocytic leukemia (B-ALL) is an aggressive lymphoproliferative bone marrow (BM) malignancy that is commonly initiated by the Philadelphia chromosome p190 BCR-ABL translocation." (PMID 32695673, 2020). "Here, we used an in vitro co-culture model based on non-edited NK cell–naïve mouse BCR/ABLp185+ B-cell acute lymphoblastic leukaemia (B-ALL) cells to investigate the primary interaction of tumour and NK cells." (PMID 39642167, 2025).
chronic eosinophilic leukemia (8 papers, 2013 to 2024). "During the past decade, the tyrosine kinase inhibitor (TKI) imatinib has been successfully used for the treatment of patients with BCR/ABL1+ chronic myeloid leukemia (CML) and for the treatment of FIP1L1/PDGFRA+ chronic eosinophilic leukemia (CEL)." (PMID 25605011, 2015). "Many of these breakpoints corresponded to known gene fusions, including BCR/ABL1 in CML, FIP1L1/PDGFRA in eosinophilic leukemia, and NPM1/ALK in anaplastic large cell lymphoma (ALCL)." (PMID 23637631, 2013).
malaria (8 papers, 2014 to 2022). Malaria is a serious and sometimes fatal disease caused by a parasite that commonly infects a certain type of mosquito which feeds on humans. "Consistent with the observation of febrile malaria children in Mali, malaria induces the activation of Th1 cytokines and Tfh-1 cells that contribute to the expansion of T-bethi atypical MBCs, also causing reduced BCR signaling." (PMID 29844379, 2018). "Here, we generated an immunoglobulin heavy chain knock-in mouse with a BCR that recognizes MSP1 of the rodent malaria parasite, Plasmodium chabaudi." (PMID 30387712, 2018). "In addition, the relationship between IG V gene usage and functional activity has only previously been explored by studying BcR from B cells of malaria-infected or -immunized subjects." (PMID 33048842, 2020). "By analyzing Abs elicited in response to a malaria vaccine, our findings confirm the specificity of our approach for identifying antigen-specific serum peptides, using a combination of proteomics, bulk BcR sequencing, and single B cell sequencing." (PMID 33048842, 2020). "Engagement of the BCR induced robust calcium mobilization in cMBC; this change in calcium levels upon BCR stimulation was markedly reduced in atMBC, as previously reported in subjects with malaria." (PMID 30091725, 2018). "Thus, T-bet+ B cells, even in the context of malaria, are likely to be a normal component of the immune compartment that becomes activated and expands, most probably in response to BCR, endosomal TLR, and IFNγ or IL-21 stimulation." (PMID 30387712, 2018). "On the other hand, there is evidence that atypMBCs from malaria-exposed individuals may contribute to antibody production, since as for cMBCs, their BCR sequences can be matched to circulating plasma antibodies." (PMID 25050555, 2014).
viral infection (8 papers, 2019 to 2024). "We show that both unswitched and switched memory B cells are highly activated, and have lost expression of inhibitory receptors, and the unswitched memory population has enhanced BCR signaling with viral infection." (PMID 37638016, 2023). "We further demonstrate that with severe viral infection DN subsets are at a heightened level of activation, display changes in immunoglobulin class isotype frequency and have functional BCR signaling." (PMID 36131937, 2022). "With severe viral infection, the B cells within each DN subset are at a heightened level of activation, display changes in immunoglobulin class isotype frequency and possess the ability to signal through the BCR." (PMID 36131937, 2022). "To determine if DN2 or any of the B cells within the different DN subsets display enhanced BCR signaling with severe viral infection, we calculated the fold difference of pSYK and pPLγC2 between unstimulated and BCR-stimulated B cells and compared these values between cohorts." (PMID 36131937, 2022). "In addition, both BCR-ABL sgRNA_1 and BCR-sgRNA_2 virus infections showed considerable gene editing efficiency, with 53% and 97.5% editing of the cell pools shown by TIDE analysis, respectively." (PMID 32485885, 2020). "Thus, high level of mutations were commonly seen in the antibody repertoires after virus infection or vaccinations, including the BCR repertoires after hepatitis B vaccinations." (PMID 33519772, 2020). "It has been reported that DNA damage response pathways, heat shock stress, BCR/ABL oncogene, and bacterial/viral infections can all participate in regulating MICA/B expression." (PMID 31088566, 2019). "Using the proposed workflow to utilize BCR/TCR methods combined with alignments and BLASTp could help to pinpoint the type of viral infection." (PMID 38307916, 2024). "We have previously reported that Double Negative B cells signal via the BCR during viral infection; however, the BCR signaling capacity of unswitched memory B cells during viral infection has not been reported." (PMID 37638016, 2023). "Thus, despite residing at a higher activation level as observed above (CD69), DN2 cells do not display an enhancement in BCR signaling with severe viral infection." (PMID 36131937, 2022). "This suggests that DN2 cells naturally have the largest capacity to signal through the BCR compared to other DN subsets, a process which may be independent of traditional inhibitory receptors (CD22, CD72, FcRL5) and/or that the function of inhibitory receptors is impaired during viral infection." (PMID 36131937, 2022). "The role of MAVS downstream of BCR stimulation was recognized in absence of IFN, indicative of a path for MAVS activation that is independent of viral infection." (PMID 37610299, 2023).
lymph node metastasis (7 papers, 2015 to 2024). "High SPAG5 expression was significantly associated with lymph node metastasis, clinical stage, Gleason score, and BCR." (PMID 27037000, 2016). "Dysregulation of TMPO-AS1 or other genes that interact with TMPO-AS1 in clinical specimens (PANTs: paired adjacent normal tissues, OS: overall survival, LNM: lymph node metastasis, BCR: biochemical recurrence)." (PMID 36467407, 2022). "According to a systematic review, ECE, SVI, and lymph node metastasis were statistically significant for BCR free survival." (PMID 32756597, 2020). "And multifocal status, LVI, pathologic T stage, and lymph node metastasis appeared to be the most potent factors indicating BcR/BcPD, whether in univariate or multivariate logistic regression analyses." (PMID 37464189, 2024). "Microarray data indicated that BCOX1 is significantly increased in patients with lymph node metastasis, higher Gleason score and BCR compared with patients without lymph node metastasis, BCR, and with lower Gleason score, respectively." (PMID 26338045, 2015).
CNS leukemia (6 papers, 2014 to 2024). "Moreover, 50% of the relapsed children had BCR::ABL1 or TCF3:: PBX1 fusion genes as a high-risk factor for CNS leukemia relapse, consistent with literature reports." (PMID 38519960, 2024). "Seven patients (9.8%) were diagnosed with CNS leukemia (e.g., CNS2 and CNS3), including 3 with T-ALL, 4 with B-ALL, 1 with BCR-ABL+ disease, and 1 with TEL-ABL+ disease." (PMID 35733807, 2022). "The remaining six patients in the HLA-matched HSCT group and two in the haploidentical HSCT group are still alive; three of them have central nervous system leukemia (CNSL), and five are BCR-ABL fusion gene-positive." (PMID 26208715, 2015).
follicular lymphoma (6 papers, 2019 to 2024). Follicular lymphoma is a form of non-Hodgkin lymphoma characterized by a proliferation of B cells whose nodular structure of follicular architecture is preserved. "DLBCL and high-grade follicular lymphoma patient samples were also sensitive to inhibition of BCR signaling with PI3Ki, BTKi, or SYKi in combination with venetoclax." (PMID 38893249, 2024). "In follicular lymphoma, MYOF has been identified as a self-antigen that can be recognized by surface BCR of malignant B-cell clone from a patient with follicular lymphoma." (PMID 31828126, 2019). "Recurrent mutations of genes involved in epigenetic regulation (e.g. KMT2D, CREBBP, and EZH2), JAK-STAT pathway (e.g. SOCS1, STAT6), immune signaling (i.e. TNFRSF14), and BCR/NFKB signaling (e.g. CARD11, CD79B) were previously reported in follicular lymphoma cases." (PMID 35795062, 2022).
lymphoid neoplasm (6 papers, 2018 to 2025). A neoplasm composed of a lymphocytic cell population which is usually malignant (clonal) by molecular genetic and/or immunophenotypic analysis. "To dissect the individual contribution of STAT5A and STAT5B to lymphoid tumor formation, we injected Stat5a−/−, Stat5b−/−, or wt BCR/ABLp185+ cell lines subcutaneously into NSG mice." (PMID 30679796, 2019). "Notably, BCR-PDGFRA, BCR-JAK2, and BCR-RET fusions have been established as additional drivers of myeloid and lymphoid neoplasms, while BCR-NTRK2 was identified as a potential driver of glioblastoma." (PMID 35574218, 2022). "This may suggest a lack of complete IGH and IGK/L rearrangements in immature lymphoid neoplasms, where transformation likely occurred prior to BCR rearrangement (before the pre-B stage)." (PMID 30285677, 2018).
pancreatic cancer (6 papers, 2010 to 2023). "There was no literature about the role of C2 in pancreatic cancer, but there was data showing C2 has a role in amplifying BCR signal transduction in each subpopulation of B-2 cells, but not B-1 cells." (PMID 37034706, 2023).
colon carcinoma (5 papers, 2020 to 2025). "BCR was identified as a DDR1 target in colon carcinoma cells using quantitative phosphoproteomics to identify proteins phosphorylated in response to DDR1 activation." (PMID 34941574, 2022). "A recent study showed DDR1 as a therapeutic target in colon cancer, activating BCR signaling downstream." (PMID 35664781, 2022).
Ewing sarcoma (5 papers, 2005 to 2022). A small round cell tumor that lacks morphologic, immunohistochemical, and electron microscopic evidence of neuroectodermal differentiation. "Characterization of the EWS-FLI1 fusion sites of 42 pediatric and young adult Ewing sarcoma patients and seven cell lines revealed a clustering in the 5′ region of the EWS-breakpoint cluster region (BCR), in contrast to random distribution of breakpoints in the FLI1-BCR." (PMID 23441188, 2013). "On the other hand, they similarly analyzed the distance between the EWS and FLI1 loci in lymphocytes, which, they concluded, was larger than that between BCR and ABL48, although the precursor of Ewing sarcoma cells is not of lymphoid lineage." (PMID 36042341, 2022).
gastric cancer (5 papers, 2018 to 2024). A primary or metastatic malignant neoplasm involving the stomach. "Clonal BCR/TCR rearrangements were detected in several blast phase CML lines and unexpectedly, one gastric cancer cell line (KE-97), reflecting a lymphoid origin of these cells." (PMID 30285677, 2018).
glioma (5 papers, 2013 to 2024). A benign or malignant brain and spinal cord tumor that arises from glial cells (astrocytes, oligodendrocytes, ependymal cells). "Targeted agents like dasatinib for BCR::ABL1 ALL, selumetinib for BRAF mutant gliomas, and PARP inhibitors for cancers with loss of homologous repair showed activity in relevant pediatric preclinical models." (PMID 39510293, 2024). "In the TCGA-glioma dataset, risk Scores were significantly correlated with age, Grade, survival status, IDH status, MGMT status, ATRX status and BCR status." (PMID 36778644, 2023).
lung adenocarcinoma (5 papers, 2010 to 2025). A carcinoma that arises from the lung and is characterized by the presence of malignant glandular epithelial cells. "A previously unidentified function of KLHL7 (Kelch Like Family Member 7) and KLHL11, components of the BCR (BTB-CUL3-RBX1) E3 ubiquitin ligase complex, in lung adenocarcinoma genomic instability was also suggested (q = 0.0003, 0.04, respectively)." (PMID 34070461, 2021). "Our approach is tested on gene expression data on i) acute lymphocytic leukemia (ALL) with and without BCR/ABL gene rearrangement and ii) lung adenocarcinoma with and without EGFR mutation." (PMID 20809931, 2010). "Whether BCR downregulation leads to Rac1 activation in lung adenocarcinoma has not yet been investigated." (PMID 38612674, 2024).